ELAC1 (elaC ribonuclease Z 1)
Description:
Zinc phosphodiesterase, which displays some tRNA 3'-processing endonuclease activity. Specifically involved in tRNA repair: acts downstream of the ribosome-associated quality control (RQC) pathway by removing a 2',3'-cyclic phosphate from tRNAs following cleavage by ANKZF1. tRNAs are then processed by TRNT1.
Synonyms: D29
Tractability: Small molecule: it has a binding pocket of medium quality. PROTAC: its protein half-life has been measured.
Gene: Protein-coding gene on chromosome 18 (50,967,989 to 50,988,991, forward strand). Ensembl gene ENSG00000141642.
Subcellular location: Cytoplasm, cytosol; Nucleus
Subcellular location (Human Protein Atlas): Nucleoplasm; Cytosol
Gene Ontology:
Molecular function: 3'-tRNA processing endoribonuclease activity; tRNA-specific ribonuclease activity; RNA endonuclease activity producing 5'-phosphomonoesters, hydrolytic mechanism
Biological process: rescue of stalled ribosome; tRNA 3'-end processing
Cellular component: cytosol; nucleoplasm; nucleus
Genetic constraint (gnomAD): Loss-of-function variants: 18 observed, 25.55 expected, observed/expected ratio (o/e) 0.7, 90% interval 0.49 to 1.04. The upper end of that interval is the gene's LOEUF score, 1.04, which puts it in group 4 of 6, group 1 being the genes least tolerant of losing a copy. Missense variants: 400 observed, 456.35 expected, observed/expected ratio (o/e) 0.88, 90% interval 0.81 to 0.95. Synonymous variants: 148 observed, 169.95 expected, observed/expected ratio (o/e) 0.87, 90% interval 0.76 to 1.
Homologues: Orthologues: chimpanzee ELAC1 (99% identical), macaque ELAC1 (99% identical), pig ELAC1 (96% identical), dog ELAC1 (95% identical), guinea pig ELAC1 (94% identical), rat Elac1 (92% identical), mouse Elac1 (92% identical), rabbit ELAC1 (90% identical), tropical clawed frog elac1 (70% identical), zebrafish elac1 (58% identical). Paralogues in human: ELAC2 (26% identical).
Diseases named in the same sentence as ELAC1 in open-access papers:
ELAC1 is named in the same sentence as 6 diseases in open-access papers, as found by Europe PMC text mining. Sharing a sentence is not in itself a finding about the gene and the disease. The quoted sentences say what the papers report.
lung carcinoma (2 papers, 2011 to 2012). "This conclusion is consistent with its low tRNA processing efficiency in vitro and with the fact that its gene (ELAC1) is part of a homozygous deletion in a lung cancer cell line, and thus apparently dispensable for cell survival and growth." (PMID 21559454, 2011).
colorectal cancer (1 paper, 2007). A primary or metastatic malignant neoplasm that affects the colon or rectum. "ELAC1, encoding an RNA processing enzyme, is located on the chromosome band 18q21, which chromosomal loss has previously been linked to poor prognosis in colorectal cancer." (PMID 17201907, 2007).
tumor (2 papers, 2007 to 2023). "Both ELAC1 and MZF1 were associated with PFI among the luminal A tumor samples in site-specific analyses." (PMID 36936429, 2023). "These included a DMR within the promoter of ELAC1 that was associated with PFI among the luminal A tumor samples, but not among the luminal B and basal-like samples." (PMID 36936429, 2023).
ELAC1 also shares sentences with these, for which no sentence is quoted: cancer (2 papers); esophageal cancer (1); osteosarcoma (1).